CD4 (CD4 molecule)
Diseases named in the same sentence as CD4 in open-access papers (continued):
Sharing a sentence is not in itself a finding about the gene and the disease.
autoimmune disease (continued). "In SLE, an autoimmune disease mainly driven by autoreactive CD4+ T cells and B cells, studies revealed an increased level of glycolysis and mitochondrial activity of CD4+ T cells of lupus patients and the lupus-prone mouse model." (PMID 34385998, 2021). "Expanded CD4+CD28null T lymphocytes are found in the tissues and peripheral blood of patients with many autoimmune diseases, such as rheumatoid arthritis (RA)." (PMID 34202487, 2021). "Although MS is considered a Th1 autoimmune disease in which prevails a CD4+ immune response, CD8+ T cells seem to play a pivotal role in the pathogenesis of major depressive disorder (MDD)." (PMID 34093579, 2021). "Accordingly, IL-9-producing CD4(+) T cells and IL-9 appear to be new therapeutic targets in allergic or autoimmune diseases." (PMID 33941281, 2021). "An autoimmune disease model in the brain recently reported the similar findings that CD47-/- CD4+ T cells were activated and produced even larger amounts of cytokines compared to WT mice." (PMID 34093583, 2021). "Recently, elevated IL-6 receptor expression on CD4+ T cells was reported to promote Th17 cell-driven inflammation by increasing IL-17 production in autoimmune diseases." (PMID 34913099, 2021). "With advances in CD4+ T cell research, Th17 cells have been identified as a separate CD4+ cell subpopulation that is closely related to autoimmune diseases." (PMID 35058928, 2021). "Expansions of CD4+ LGL rarely manifest neutropenia or autoimmune diseases, but frequently co-occurred with solid tumors and often displayed STAT5B but not STAT3 mutations." (PMID 34359799, 2021). "GM-CSF produced by autoreactive CD4-positive T helper cells is involved in the pathogenesis of autoimmune diseases, such as multiple sclerosis." (PMID 34285924, 2021). "Recently, an unusual subset of cytotoxic CD4+ T cells has been described in patients with two rare, fibrosis-prone autoimmune disorders: immunoglobulin G4-related disease (IgG4-RD) and systemic sclerosis (SSc)." (PMID 33648559, 2021). "The identification of the peptide epitopes presented by major histocompatibility complex class II (MHCII) molecules that drive the CD4 T cell component of autoimmune diseases has presented a formidable challenge over several decades." (PMID 33095259, 2021). "The central role of CD4 T cells in orchestrating the immune response in allergy, autoimmune disease and the antigen-drug antibody response to biologics is clear." (PMID 34567009, 2021). "Recent studies in autoimmune diseases suggest that increased expression of TLR2 in CD4+ T cells enhances immune reactivity and promotes IL-17 expression through upregulating H3K4 while downregulating H3K9 tri-methylation level in SLE." (PMID 34367251, 2021). "Autoimmune diseases are disorders in which the body's immune system attacks its own cells and organs, and autoreactive T lymphocytes—particularly CD4/helper T cells—are now known to be the critical leukocytes causing these disorders." (PMID 34008922, 2021). "Experimental autoimmune encephalomyelitis (EAE) is an animal model of multiple sclerosis (MS) and a CD4+ T cell-mediated autoimmune disease." (PMID 33927721, 2021). "T-helper 17 (Th17) cells are a subset of CD4+ T cells and were found to be related to the pathogenesis of autoimmune diseases and inflammatory diseases such as AS, rheumatoid arthritis (RA), and inflammatory bowel disease (IBD)." (PMID 34589304, 2021). "Identification of the CD4 T cell peptide epitopes driving autoimmune diseases has been surprisingly difficult over the years." (PMID 33095259, 2021). "Increasing evidence show that long noncoding RNAs (lncRNAs) can regulate immune responses and take part in some autoimmune diseases, while little is known about the lncRNA expression and function in CD4+ T of SLE." (PMID 34707498, 2021).
autoimmune disease (continued). "Although type 1 diabetes is thought to be an organ-specific autoimmune disease, mediated by effective CD4+ and CD8+ T cells, it has recently become clear that B cells participate in the initiation and progress of this disease." (PMID 34778464, 2021). "MicroRNA miR-155 is an important regulatory molecule in the immune system and is highly expressed and functional in Th17 cells, a subset of CD4+ T helper cells which are key players in autoimmune diseases." (PMID 34075120, 2021). "An increased proportion of CD4+ or CD8+ Tscms has also been observed in patients with autoimmune disease, such as systemic lupus erythematosus (SLE), type 1 diabetes, aplastic anaemia, immune thrombocytopenia and rheumatoid arthritis." (PMID 34527440, 2021). "Here, using mice carrying conditional ablation of RelB in T cells, we evaluated its role in the development of conventional CD4+ T (Tconv) cells and their function in autoimmune diseases." (PMID 34608221, 2021). "Naive CD4+ T cells differentiate into various Th cell subsets and play various roles in autoimmune diseases." (PMID 34721413, 2021). "Perhaps of greatest importance, however, is the dual effect of UMCD6 in both suppressing autoimmune diseases through its effects on differentiation of effector CD4+ cell subsets and activating the anticancer cytotoxic properties of CD8+ and NK cells." (PMID 33497367, 2021). "Th17 cells are a subset of CD4+ helper T cells, which are widely believed to induce inflammation in the pathogenesis of autoimmune diseases by producing cytokines such as IL‐17, TNF‐α, and IL‐6." (PMID 33728820, 2021). "Type 1 diabetes is another prototypic autoimmune disorder mediated by Th1 CD4 T cells and CTLs where cell therapy approaches including MAPC cells and Tregs show promise." (PMID 34539651, 2021). "T1DM is an autoimmune disease driven by CD4+ T cells that destroy insulin-secreting beta cells in the pancreas." (PMID 33672515, 2021). "EAU is a CD4+ T lymphocyte-mediated autoimmune disease model that recapitulates many features of NIU and can be used to study the pathogenesis, specifically the cellular interactions to retinal-specific antigens from immunologically privileged sites." (PMID 34502490, 2021). "NFAT5 is known to play a critical role in the high salt-mediated exacerbation of autoimmune diseases along with the induction of inflammatory Th17 CD4+T cell phenotype." (PMID 33918403, 2021). "Treg cells are a subtype of CD4+ T cells that have a powerful ability to maintain immunological self-tolerance and suppress the development of various autoimmune diseases." (PMID 35096296, 2021). "In mice, the miR-10a targets Prdm1 gene to suppress the production of IL-10 in CD4+ T cells, playing important roles in regulation of intestinal homeostasis and in pathogenesis of autoimmune diseases." (PMID 34950131, 2021). "The interactions of CD4+ T cells and B cells are fundamental for the generation of protective antibody responses, as well as for the development of harmful autoimmune diseases." (PMID 32868910, 2021). "Dysregulation of C3 and CD46 in CD4+ T cells has been reported to contribute to Th1‐mediated autoimmune diseases." (PMID 33682108, 2021). "It is known that CD8a-SIRPα+ cDCs mainly induce CD4+ T cell responses, which is an important effector T cell population in autoimmune diseases, whereas CD8a+SIRPα- cDCs has greater ability to induce a CD8+ T cell response." (PMID 34093583, 2021). "An important role in the immune responses is played by conventional dendritic cells (cDC) that interact with CD4+ T cells, known to be central in the pathogenesis of autoimmune diseases such as SS." (PMID 34208031, 2021). "Like in several autoimmune diseases, an impairment in natural killer (NK) cells, as well as a significant increase in the CD4+ lymphocyte and a decrease in the CD8+ lymphocyte subsets, was observed in migraine patients." (PMID 34749743, 2021).
autoimmune disease (continued). "The EAE model is an autoimmune disease model mediated by CD4+ T helper (Th) cells, characterized by the local infiltration of T lymphocytes in the CNS, and recognized as a classical animal model to study the autoimmune disease." (PMID 34955841, 2021). "Given the key function of KDM6A in regulating CD4+ T cells, concluded that KDM6A likely regulates multiple immune response genes in autoimmune disease susceptibility." (PMID 34051747, 2021). "Studies have shown that CD4+CXCR5+ cell percentage in CD4+T cells is elevated in the blood of patients with autoimmune diseases such as Systemic Lupus Erythematosus (SLE) and Myasthenia Gravis (MG) and is associated with antibody production." (PMID 34630268, 2021). "Since the studied autoimmune diseases typically involve more than one type of CD4+ T-cell subtype, we next summed up the Z-scores of all the models within a disease for each drug target." (PMID 33483502, 2021). "Recent studies have shown that newly discovered cells such as regulatory T cells (CD4+CD25+HighFoxP3+) or Th17 (CD4+IL-17+) play an important role in inducing autoimmune diseases." (PMID 34493981, 2021). "CD4 T cells are pivotal in adaptive immune responses during infection, autoimmune diseases, cancer, and vaccinations." (PMID 34402793, 2021). "For this purpose, we evaluated CD4+ T cells, which are indispensable in a number of autoimmune diseases." (PMID 33498298, 2021). "CD4+ T cells are effective mediators of well-known autoimmune diseases in the nervous system, such as multiple sclerosis and narcolepsy, which are involved in developing microglia." (PMID 34924996, 2021). "From a functional perspective, Tph cells are defined as CD4+ T cells that provide help to B cells in inflamed tissues in autoimmune diseases." (PMID 32868910, 2021). "A new B‐cell subpopulation has recently been described, namely CD19+ PD‐L1+ regulatory B cell, which requires PD‐L1 expression to regulate CD4+ PD‐1+ T follicular helper (Tfh) cell expansion and differentiation and to suppress autoimmune diseases." (PMID 32937024, 2021). "Tregs are involved in cancers and many other autoimmune diseases and also be known as the immunosuppressive subset of CD4+ T cells that maintain the immune homeostasis by suppressing the function of T cells." (PMID 33869044, 2021). "Staphylococcal super-antigens trigger the CD4 T-cell activation, increase auto-reactive T-cells, and leads to the exacerbation of autoimmune disease." (PMID 34847159, 2021). "Subsets of CD4+ T cells, including Th17 cells and Tregs, are recognized as important targets for the treatment of autoimmune disease; however, few studies have concentrated on the role of naïve CD4+ T cells." (PMID 33717180, 2021). "The priming of autoreactive CD4+ T cells by antigen-presenting cells (APCs) is a key event in many autoimmune diseases." (PMID 34491911, 2021). "In the SS immunopathogenesis, the population of lymphocytes more strongly involved is that of CD4+ T lymphocytes, as in other autoimmune diseases." (PMID 34208031, 2021). "Further, we provide a detailed review of the roles of redox regulation in the glycolytic/PPP equilibrium in CD4+ T cells, focusing on rheumatoid arthritis (RA) as a model autoimmune disease." (PMID 33717180, 2021). "Utilizing peptide-HLA multimer technology, antigen-specific CD4 + T cells have been demonstrated in ‘classical’ autoimmune diseases as type 1 diabetes and SLE, and also in celiac disease, Parkinson’s disease and atherosclerosis." (PMID 34972837, 2021). "Instead of analyzing Tph cells in tissues, many studies have analyzed circulating Tph (cTph) cells in the blood, which are defined as PD-1hiCXCR5− CD4+ T cells, with the aim of assessing the global activity of Tph cells in autoimmune diseases." (PMID 32868910, 2021).
autoimmune disease (continued). "IL-21, a pro-inflammatory cytokine elevated in several autoimmune disorders, shows increased plasma levels in AA, as well as IL-21-producing CD4+ T cells in the BM that are positively correlated with Th17 frequency and negatively correlated with Treg number." (PMID 33445786, 2021). "In human peripheral blood, CD4+CD25+CD127-/lowFoxp3+ Tregs account for approximately 1–2% of the total CD4+ T cells, helping to prevent autoimmune diseases by inhibiting the proliferation of effective T cells and cytokines production." (PMID 32256193, 2020). "Similar to Clostridium cluster IV, Clostridium XIVb was the most effective in generating high levels of Treg cells in the CD4+ T cell population, which are essential for maintaining immune tolerance and abrogating chronic inflammatory or autoimmune diseases." (PMID 33391265, 2020). "In parallel to Th1, some reports show that Th17 cells, a subtype of interleukin (IL)‐17 secreting CD4+ Th cells, and their relevant cytokines play important role in the severity and progression of several autoimmune diseases." (PMID 33135395, 2020). "KDM6A has been reported to have roles in the function of Treg cells and CD4 T cells in autoimmune disease and maintenance of Th17 (T-helper cell 17) CD4 T cell responses." (PMID 32731355, 2020). "Taken together, strong evidence supports a key role for memory CD4+ T cells in the pathogenesis of autoimmune diseases." (PMID 32106536, 2020). "Autoimmune diseases are characterized by regulatory deficit in both the CD4+ and CD8+ T-cell compartments." (PMID 33193343, 2020). "In autoimmune disease, dendritic cells play an indisputable role in instructing the polarization of CD4+ Th17 cells in immune response through generation of cytokines such as IL-6, IL-23, and IL-1β." (PMID 33643041, 2020). "Bifunctional cells that share lineage and phenotypic features of two canonical CD4 T cell differentiation pathways have been described previously in autoimmune disease and in other settings." (PMID 32248243, 2020). "Subsequent work in animal models of autoimmune diseases further highlighted the roles which memory CD4+ T cell play in promoting autoimmunity." (PMID 32106536, 2020). "CD4+Foxp3+ T cells were increased in SLE patients compared with organ-specific autoimmune disease controls or healthy controls." (PMID 32317002, 2020). "Among diverse CD4+ T-cell subsets, IL-17A-producing CD4+ T cells (Th17) provide protection against extracellular pathogens and fungi, but also exert detrimental roles in mediating tissue inflammation in autoimmune diseases." (PMID 31936879, 2020). "IL1β is a pro-inflammatory cytokine that has stimulatory effects and helps promote the differentiation of CD4+ T cells into T helper 1 (Th1) and Th17 lineages, both of which are known to contribute to autoimmune disease pathogenesis." (PMID 32547552, 2020). "A question central to autoimmune memory is which autoantigens the memory CD4+ T cells recognize in human autoimmune diseases." (PMID 32106536, 2020). "Memory CD4+ T cells are of great interest in the context of autoimmune diseases because of their long-lived nature, efficient responses to antigens, and unique potential to mediate recurring autoimmune responses." (PMID 32106536, 2020). "Similar to most autoimmune diseases, the autoimmunity of T1D is complicated and involves different compartments of the immune system including CD4+, CD8+ T cells, Tregs, B cells, DCs, monocyte/macrophages (Mo/Mφs), and natural killer T cells (NKTs)." (PMID 32878069, 2020). "Recent studies have provided evidence that autophagy also plays an important role in autoimmune disease by modulating the function of CD4+ T cell." (PMID 33643041, 2020). "Myasthenia gravis (MG) is a CD4+ T cell-dependent autoimmune disease resulting from aberrant immune response mediated by circulating autoantibodies at the neuromuscular junction." (PMID 32148437, 2020).
autoimmune disease (continued). "IL‐21, a CD4+ T cell–derived cytokine, is shown to enhance inflammatory response in autoimmune disease." (PMID 32881301, 2020). "Recent studies have identified and functionally characterised IL-17-expressing CD4+Th17 cells in organ-specific autoimmune diseases." (PMID 32973748, 2020). "mTOR is now well recognized as an important regulator of CD4+ T subsets that influences the development of autoimmune diseases such as MS and EAE." (PMID 32983109, 2020). "CD4+Foxp3+ Tregs which serve as a small subset of T cells play an important role in maintaining immunological tolerance and preventing autoimmune diseases in psoriasis." (PMID 32908937, 2020). "Here, we will summarize and discuss some of the most pertinent findings on memory CD4+ T cells in autoimmune diseases, with special focus on multiple sclerosis (MS) and its animal model experimental autoimmune encephalomyelitis (EAE)." (PMID 32106536, 2020). "Remarkably, MIF and PAI1 are expressed by DN T cells, together with RANTES, promoting a T-cell cytokine-enhancing effects that is involved in processes like autoimmune disease and aging, mediated by CD4+ and CD8+ T cells." (PMID 33383950, 2020). "Increasing clinical evidence demonstrated that dysfunctions of CD4+ T cells contributed to multiple chronic diseases such as type 1 diabetes and autoimmune diseases." (PMID 32878069, 2020). "Systemic sclerosis (SSc) is a genetically complex autoimmune disease mediated by the interplay between genetic and epigenetic factors in a multitude of immune cells, with CD4+ T lymphocytes as one of the principle drivers of pathogenesis." (PMID 32977850, 2020). "Autoreactive memory CD4+ T cells have been studied in patients in several autoimmune disease conditions." (PMID 32106536, 2020). "Experimental autoimmune uveitis (EAU) is a CD4+ T cell–mediated organ-specific autoimmune disease and has been considered as a model of human autoimmune uveitis." (PMID 33117376, 2020). "Myasthenia gravis (MG) is a CD4+ T cell-dependent autoimmune disease and intravenous immunoglobulin (IVIg) has been the mainstay of immunotherapeutic therapy." (PMID 32148437, 2020). "Despite high PD-1 expression, Egr2/3−/− MP CD4 T cells are highly inflammatory leading to the development of autoimmune disease." (PMID 32709717, 2020). "IL6 promotes the differentiation of CD4+ T-helper (Th) cells into Th17 cells, thereby contributing to the pathogenesis of autoimmune diseases." (PMID 32458144, 2020). "Depletion of CD4+CD25+ T cells gives rise to a broad-spectrum of autoimmune diseases in mice, whereas reconstitution of CD4+CD25+ T cells prevents autoimmune disease." (PMID 32650487, 2020). "Self-reactive CD4+ T cells are known to be rare, and several autoimmune diseases can be initiated through recognition of multiple target antigens." (PMID 32423478, 2020). "Recent studies have identified that miRNAs can modulate CD4+ T cell activation and differentiation, and can regulate the pathogenesis of autoimmune diseases through the modulation of CD4+ T cell differentiation." (PMID 32269577, 2020). "The abnormal hyperactivity of Tfh cells as a CD4+ T subpopulation leads to the development of autoimmune diseases including IBD, autoimmune liver disease, and rheumatoid arthritis (RA), which were induced by abnormal expressions of related signaling proteins." (PMID 32581849, 2020). "Specifically, autoimmune memory CD4+ T cells become “stumbling blocks” that hinder most attempts to treat or heal T1D and other autoimmune diseases." (PMID 32878069, 2020). "This approach has been used successfully in human systemic lupus erythematosus, which is also an autoimmune disease, and in CD4+ T cells differentiating to Th17 in the presence of an inhibitor of Th17 response." (PMID 31968593, 2020). "It has also been repeatedly shown that lower affinity T cells are capable of the host of effector functions needed for CD4+ T cell mediated autoimmune disease." (PMID 33120989, 2020).